ZNF318 (zinc finger protein 318)
Description:
[Isoform 2]: Acts as a transcriptional corepressor for AR-mediated transactivation function. May act as a transcriptional regulator during spermatogenesis and, in particular, during meiotic division. [Isoform 1]: Acts as a transcriptional coactivator for AR-mediated transactivation function. May act as a transcriptional regulator during spermatogenesis and, in particular, during meiotic division.
Synonyms: HRIHFB2436; ZFP318; TZF
Tractability: PROTAC: UniProt records ubiquitination sites on it; ubiquitination databases record sites on it; its protein half-life has been measured.
Gene: Protein-coding gene on chromosome 6 (43,307,134 to 43,369,647, reverse strand). Ensembl gene ENSG00000171467.
Subcellular location: Nucleus
Subcellular location (Human Protein Atlas): Nucleoplasm; Cytosol
Gene Ontology:
Molecular function: protein homodimerization activity; nucleic acid binding; zinc ion binding
Biological process: negative regulation of DNA-templated transcription; positive regulation of DNA-templated transcription
Cellular component: nucleoplasm; nucleus
Genetic constraint (gnomAD): Loss-of-function variants: 52 observed, 120.2 expected, observed/expected ratio (o/e) 0.43, 90% interval 0.34 to 0.55. The upper end of that interval is the gene's LOEUF score, 0.55, which puts it in group 2 of 6, group 1 being the genes least tolerant of losing a copy. Missense variants: 2,808 observed, 2,859.6 expected, observed/expected ratio (o/e) 0.98, 90% interval 0.95 to 1.01. Synonymous variants: 1,090 observed, 1,055.5 expected, observed/expected ratio (o/e) 1.03, 90% interval 0.98 to 1.09.
Homologues: Orthologues: chimpanzee ZNF318 (99% identical), macaque ZNF318 (97% identical), dog ZNF318 (86% identical), pig ZNF318 (84% identical), rabbit ZNF318 (77% identical), rat Zfp318 (72% identical), guinea pig ZNF318 (72% identical), mouse Zfp318 (72% identical), zebrafish znf318 (24% identical), tropical clawed frog znf318 (16% identical), Caenorhabditis elegans D1044.6 (9% identical), Drosophila melanogaster CG9776 (8% identical).
Diseases named in the same sentence as ZNF318 in open-access papers:
ZNF318 is named in the same sentence as 10 diseases in open-access papers, as found by Europe PMC text mining. Sharing a sentence is not in itself a finding about the gene and the disease. The quoted sentences say what the papers report.
breast carcinoma (4 papers, 2020 to 2024). "In addition, ZNF318 was previously implicated in breast cancer with two positions: G1274R and N632S46." (PMID 33168853, 2020). "Epigenetic MR analysis identified four CpG sites, cg03260624 near CDC7 gene, cg10816169 near ZNF318 gene, cg03345232 near RIN3 gene, and cg26312998 near RP11-867G23.13 gene, where genetically predicted epigenetic modifications were associated with an increased breast cancer incidence risk." (PMID 35708873, 2022). "No previous study has reported the role of ZNF318 in breast cancer development." (PMID 35708873, 2022).
acute myeloid leukaemia (1 paper, 2022). "Screening 534 acute myeloid leukaemia (AML) genomes for variants in ZNF318 and HIST2H3D identified only one possible oncogenic mutation in ZNF318, showing that although these variants are under selection in HSC/MPPs, they do not necessarily contribute to malignancy." (PMID 35650442, 2022).
hearing loss (1 paper, 2021). "It is therefore possible that the association of MYO3B, ARID5B and ZNF318 with tinnitus is secondary to their role in hearing since tinnitus is usually manifested when there is a hearing loss present." (PMID 33742053, 2021).
leukemia (1 paper, 2024). A malignant (clonal) hematologic disorder, involving hematopoietic stem cells and characterized by the presence of primitive or atypical myeloid or lymphoid cells in the bone marrow and the blood. "ZNF318 mutations have been linked to altered gene regulation, potentially affecting leukemia progression and patient outcome." (PMID 39519198, 2024).
cancer (2 papers, 2020 to 2024). A tumor composed of atypical neoplastic, often pleomorphic cells that invade other tissues. "The genes in that amplified segment are ABBC10, a transmembrane transporter with implication on anti-cancer agent transfer and ZNF318, coding for the best substrate for deacetylation enzymes (HDAC8)." (PMID 33168853, 2020).
ZNF318 also shares sentences with these, for which no sentence is quoted: infection (2 papers); breast (1); lupus (1); pancreatic cancers (1); Tinnitus (1).